NLRP3 (NLR family pyrin domain containing 3)
Diseases named in the same sentence as NLRP3 in open-access papers (continued):
Sharing a sentence is not in itself a finding about the gene and the disease.
Shock (4 papers, 2021 to 2024). The state in which profound and widespread reduction of effective tissue perfusion leads first to reversible, and then if prolonged, to irreversible cellular injury. "During septic shock, the activity of the inflammasome, particularly the NLRP3 inflammasome, is dysregulated, which contributes to immune system imbalance and monocyte deactivation." (PMID 39408970, 2024). "JNK/NLRP3 inflammatory signaling plays an important role in mediating hemorrhagic shock-induced tissue injury and JNK is activated by hypoxia, ROS or RNS, and/or various cytokines." (PMID 35371607, 2022). "NLRP3 inflammasome mediates the occurrence of many inflammatory diseases, including septic shock." (PMID 33717117, 2021).
Sleep apnea (4 papers, 2019 to 2022). An intermittent cessation of airflow at the mouth and nose during sleep is known as sleep apnea. "For example, a recent GWAS publication in humans indicated that molecules upstream and downstream of NLRP3 inflammasome activation are associated with oxidative saturation levels in sleep-disordered breathing." (PMID 35392608, 2022).
syphilis (4 papers, 2018 to 2026). A contagious bacterial infection caused by the spirochete Treponema pallidum. "In this study, we investigate the expression of the NLRP3 inflammasome during the development of tissue inflammation associated with syphilis, the activation of the inflammasome and release of IL-1β were estimated during T. pallidum infection in a rabbit model." (PMID 29490620, 2018). "Our results also confirmed that miR‐223‐3p negatively regulates the NLRP3 expression, by using a dual‐luciferase assay, and also that this process occurs in syphilis patients and HUVECs stimulated with rTP17." (PMID 33145937, 2020). "We found that miR‐223‐3p, which was reported to be involved in the regulation of inflammasome activation and cancer development via NLRP3 targeting, was greatly down‐regulated in syphilis patients." (PMID 33145937, 2020). "In conclusion, we found that miR‐223‐3p was significantly down‐regulated in syphilis patients when compared to healthy controls, whereas NLRP3 and caspase‐1 expression were dramatically up‐regulated in syphilis patients." (PMID 33145937, 2020). "In this study, we also investigated the effect of penicillin treatment on the expression of the NLRP3 inflammasome during the development of tissue inflammation due to syphilis." (PMID 29490620, 2018). "Taken together, our results reveal that miR‐223‐3p targets NLRP3 to suppress inflammasome activation and pyroptosis in T pallidum‐infected endothelial cells, implying that miR‐223‐3p could be a potential target for syphilis patients." (PMID 33145937, 2020). "Mechanistically, gain‐ and loss‐of‐function experiments demonstrated that miR‐223‐3p targets NLRP3 in order to suppress inflammasome activation and pyroptosis, highlighting the potential of miR‐223‐3p as a therapeutic target for the clinical treatment of syphilis." (PMID 33145937, 2020). "Therefore, investigation of the factors that regulate NLRP3 inflammasome activation and pyroptosis may lead to the development of effective therapy strategies for syphilis patients." (PMID 33145937, 2020). "Most importantly, a notable negative correlation was observed between miR‐223‐3p and NLRP3, caspase‐1, and IL‐1β, respectively, in the serum of syphilis patients and healthy controls." (PMID 33145937, 2020).
tendinopathy (4 papers, 2023 to 2024). "In this study, we found that NLRP3 controls the production of IL-1β in a mouse model of tendinopathy by sterile extracellular matrix degradation, while an alternative ASC-dependent inflammasome controls IL-18 production." (PMID 39468985, 2024). "Here, we aimed to investigate the implication of NLRP3 in a mouse model of tendinopathy by collagenase degradation of the extracellular matrix in the Achilles’ mice tendon." (PMID 39468985, 2024). "Among the various inflammatory vesicle complexes, the NLRP3 inflammatory vesicle complex is the most common one in the inflammatory phase of tendinopathies." (PMID 37744452, 2023). "However, few models have studied the implication of NLRP3 in tissue damage-induced inflammation, particularly the implication of NLRP3 in tendinopathies." (PMID 39468985, 2024). "Therefore, NLRP3 plays an important regulatory role in the inflammatory mechanism of tendinopathy." (PMID 37744452, 2023). "In conclusion, we found that the NLRP3/ASC-inflammasome controls the production of IL-1β, meanwhile, another ASC-dependent inflammasome is required to produce IL-18 in tendinopathy induced by sterile tissue degradation of the extracellular collagen matrix." (PMID 39468985, 2024). "In particular, NF-κB, NLRP3, p38/MAPK, and signal transducer and activator of transcription 3, four common signaling pathways in tendinopathy inflammatory response, play a crucial role in the regulation and transcription of inflammatory factors." (PMID 37744452, 2023). "In our tendinopathy model, we do not know the exact signal controlling NLRP3 and potentially other ASC-dependent inflammasomes." (PMID 39468985, 2024). "The pathogenesis of tendinopathies includes degradation of extracellular matrix and inflammation, however, the role of the NLRP3 inflammasome has not being studied in the context of tendinopathies." (PMID 39468985, 2024). "The results of our study propose that pharmacologic treatment of the inflammatory response associated to tendinopathy would be ideally treated with pan-inflammasome inhibitors or therapies targeting ASC, rather than specific NLRP3 blockers or other inhibitors targeting single inflammasomes." (PMID 39468985, 2024).
thyroid (4 papers, 2024 to 2026). "This oxidative stress may initiate two key pathological processes: accumulation of ROS in thyroid cells triggers pro-inflammatory pathways (NF-κB, NLRP3 inflammasome) and enhances presentation of thyroid autoantigens." (PMID 41351775, 2025).
ulcer (4 papers, 2024 to 2025). "Both treatments significantly reduced NLRP3 levels compared to the ulcer group, indicating effective modulation of inflammasome activity and a decrease in inflammation." (PMID 40563542, 2025). "In uninfected ulcer patients, NLRP3 expression correlated with IL-1β, whereas in infected groups, active caspase-1 was closely associated with both GSDMD-N and mature IL-18, supporting canonical pyroptosis activation." (PMID 40563885, 2025). "In uninfected ulcer patients, a significant correlation was seen between NLRP3 expression and IL-1β expression." (PMID 40563885, 2025). "In addition, H. pylori infection increased the expression levels of both ASC and NLRP3 in ulcer patients." (PMID 40563885, 2025). "Additionally, NLRP3 levels were markedly higher in the ulcer group, indicating enhanced inflammasome activation closely associated with increased HMGB1 levels." (PMID 40563542, 2025). "Our findings corroborate earlier research indicating that OMP, used as a reference drug, significantly diminished the levels of HMGB1, NF-κB p65, and NLRP3 in comparison to the ulcer group and substantially reduced the levels of IL-1β, IL-6, and TNF-α in gastric mucosa." (PMID 40563542, 2025). "A direct comparison between the ulcer + OMP and ulcer + OMP-NS groups revealed that the OMP-NS formulation significantly decreased levels of HMGB1, NLRP3, NF-κB, TLR-2, MyD88, IL-1β, IL-6, and TNF-α." (PMID 40563542, 2025). "This research elucidated that the relative mRNA expression of NLRP3 and GSDMD in stomach tissue had a significant upregulation in the ulcer group compared to the control group (P < 0.001 for each)." (PMID 38457071, 2024). "The ulcer group revealed a significant increase in MDA, gastrin, NLRP3, and GSDMD and a decrease in gastric pH and GSH compared to the control group." (PMID 38457071, 2024).
urolithiasis (4 papers, 2016 to 2025). Stone(s) within the urinary tract. "Their Cua/Ccr increased to 44.0 and 73.6%, suggesting that the excess Uua excretion could form UA precipitates and cause urolithiasis, activating tubular NLRP3 inflammasome, thereby causing EIAKI." (PMID 39361182, 2025). "After blocking the NLRP3 inflammasome, there was less oxidative damage and higher anti-inflammatory infiltration in the kidneys of experimental mice, which exhibits the potential prospects of immunotherapy in the treatment of urolithiasis." (PMID 40612664, 2025). "Notably, we found that ceftriaxone-induced urolithiasis was associated with a high risk of AKI and NLRP3-mediated inflammasome and oxidative stress injury were of major importance in the pathogenesis." (PMID 32695257, 2020). "Although the common periodontal pathogens in dental plaque, Porphyromonas gingivalis and Treponema denticola, activate NLRP3 inflammasome in human macrophages, dental calculus might contribute to inflammation in gingival tissue by further activating NLRP3 inflammasome." (PMID 27632566, 2016).
Zinc deficiency (4 papers, 2014 to 2024). A deficiency of the essential metal Zinc; an essential cofactor for many enzymes. "Zinc deficiency acts as an NLRP3 activating and potentiating stimuli in macrophages, microglia, and mixed glia, while zinc supplementation is inhibitory of NLRP3 activation." (PMID 33597269, 2021). "Critically, we found that the combination of zinc deficiency and amyloidopathy is sufficient to induce NLRP3 activation and IL-1β release in mixed glia (and macrophages)." (PMID 33597269, 2021). "We show here that depletion of zinc from macrophages, a paradigm for zinc deficiency, also activates the NLRP3 inflammasome and induces IL-1β secretion." (PMID 24481454, 2014). "We then hypothesized that the effects of zinc deficiency may be common with NLRP3-dependent age-related cognitive decline." (PMID 33597269, 2021).
abortion (3 papers, 2020 to 2024). the ending of pregnancy by removing a fetus or embryo before it can survive outside the uterus. "By investigating rat abortion model, the results showed NLRP1 and NLRP3 expression in abortion rat uterus increased (∗P < 0.05, ∗∗P < 0.01), TFR1 and ACSL4 expression increased and GPX4 expression was decreased (∗P < 0.05, ∗∗P < 0.01), that compared with the control group." (PMID 34490257, 2021).
Acidosis (3 papers, 2013 to 2023). Abnormal acid accumulation or depletion of base. "Acidosis is also regarded as an inducer of NLRP3 inflammasome activity." (PMID 34059091, 2021). "Acidosis was also recently described as an inducer of the NLRP3 inflammasome." (PMID 24022484, 2013). "Acidosis was also recently described as a danger signal that could activate the NLRP3 inflammasome." (PMID 24022484, 2013).
acute respiratory failure (3 papers, 2021 to 2025). Life-threatening respiratory failure that develops rapidly. "Thus, hypothermia is an important modulating factor in the NLRP3 inflammasome activation, IL-1β release and NETs formation, preventing LPS-HVV-induced acute respiratory failure." (PMID 40236184, 2025).
aging (3 papers, 2016 to 2025). A developmental process that is a deterioration and loss of function over time. "Thus, the discovery of NLRP3 inhibitors (s) is warranted for the treatment of NLRP3 inflammasome-mediated pathobiology and its associated aging diseases." (PMID 40643515, 2025). "And inhibition of NLRP3 can promote autophagy and alleviate oxidative stress as well as aging-related diseases, indicating that NLRP3 might be a promising therapeutic target for OA." (PMID 34777685, 2021).
alcohol use disorder (3 papers, 2022). "However, despite one report suggesting a protective role of the NLRP3 inflammasome during chronic alcohol treatment in mice, the impact of inflammasome activation, in particular the impact of the NLRP6 inflammasome, on ALD progression during long-term chronic alcohol abuse is unknown." (PMID 35053298, 2022).
alopecia areata (3 papers, 2022 to 2025). Loss of scalp and body hair involving microscopically inflammatory patchy areas. "In alopecia areata animals, the NLRP3 inflammasome increased, and the NLRP3 inflammasome inhibitor (MCC950) decreased hair loss." (PMID 41462701, 2025).
amebiasis (3 papers, 2015 to 2025). A parasitic infectious disorder caused by amoebas. "A role for Crem in regulating the NLRP3 inflammasome during amebiasis was suggested by downregulation of Il1b and Nlrp3 transcripts during acute challenge." (PMID 40576353, 2025). "Our in vivo results in an animal model of acute Eh invasion and in intact human colonic biopsies cultured with the parasite indicate the NLRP3 inflammasome plays a significant role in regulating the pro-inflammatory response in acute intestinal amebiasis by regulating IL-1β responses in the colon." (PMID 25955828, 2015).
aneurysmal disease (3 papers, 2021 to 2023). "Future studies should utilize global and cell-specific knockouts of NLRP3 and other inflammasome components to clearly delineate the role of the inflammasome in aneurysmal disease." (PMID 41541085, 2023). "Additional investigation in Apolipoprotein E (ApoE) –/– mice (deficient in NLRP3, caspase recruitment domains, and caspase-1) found reduced elastic lamina degradation and MMP activation in early AAA formation, further supporting a role for the NLRP3 inflammasome in aneurysmal disease." (PMID 38275364, 2023).
angina pectoris (3 papers, 2022 to 2024). The symptom of paroxysmal pain consequent to MYOCARDIAL ISCHEMIA usually of distinctive character, location and radiation. "The NLRP3 inflammasome, in particular, has been identified as a key contributor to the pathogenesis of angina pectoris, a symptom of CAD." (PMID 39039680, 2024).
Ataxia (3 papers, 2018 to 2022). Ataxia refers to impaired coordination of voluntary muscle movement. "Genetic ablation of caspase-1 function in wobbly mice not only reinforced the role of NLRP3 in the progression of neurodegeneration, but also identified caspase-1 as a potential therapeutic target in gliosis-associated ataxias in addition to NLRP3 itself." (PMID 30097576, 2018). "Besides, researchers found that blocking NLRP3 function in vivo significantly delayed neuronal degeneration and ataxia onset in severe neurodegenerative diseases, such as cerebellar ataxias." (PMID 34436268, 2021). "In addition, we show that substantial microgliosis is triggered by the NLRP3 inflammasome pathway in the cerebellum and that blocking NLRP3 function in vivo significantly delays neuronal degeneration and the onset of ataxia in mutant animals." (PMID 30097576, 2018). "In order to assess whether aggregates are responsible for the NLRP3-mediated neuroinflammation in cerebellar ataxia or the inflammatory response is induced by neuron-derived DAMPs, different ataxia mouse models with and without the involvement of preoteinopathy need to be compared." (PMID 30097576, 2018).
autoimmune encephalitis (3 papers, 2015 to 2024). Inflammation of the brain secondary to an immune response triggered by the body itself. "In vivo, it is effective at doses ranging from 4 to 20 mg/kg in mouse models of autoimmune encephalitis, a disease of constitutive NLRP3 activation." (PMID 35739522, 2022). "In the spinal cord, the expression of NLRP3 is increased in an experimental autoimmune encephalitis model and NLRP3 knockout mice show a delayed course of a less severe disease." (PMID 26218747, 2015).
autoimmune myocarditis (3 papers, 2020 to 2025). Autoimmune myocarditis is an autoimmune disease that affects the heart. "In recent studies, miR-223-3p has been identified to ameliorate experimental autoimmune myocarditis and inflammatory damage in retinal pigment epithelium by targeting NLRP3." (PMID 40799819, 2025). "miR‐223 has previously been shown to decrease the expression of NLRP3 inflammatory corpuscles in the autoimmune myocarditis model, thus promoting the differentiation of dendritic cells (DCs) into tolerant DC phenotypes." (PMID 33047847, 2020). "miR‐223‐3p alleviated experimental autoimmune myocarditis by repressing NLRP3 inflammasome expression and promoting the polarization of DCs towards a tolerant DC phenotype." (PMID 33047847, 2020).
bone cancer (3 papers, 2021 to 2022). A primary or metastatic malignant neoplasm affecting the bone or articular cartilage. "We found that intrathecal injection of rosiglitazone reduced the mechanical hyperalgesia induced by bone cancer by activating PPAR-γ to inhibit the NF-κB/NLRP3 inflammatory axis in spinal cord neurons." (PMID 34484316, 2021). "This suggests that blocking the functional crosstalk between NF-κB and NLRP3 may reduce chronic pain induced by bone cancer." (PMID 34484316, 2021). "Mounting evidence reveal that the expression of NLRP3 inflammasome, including NLRP3, apoptosis-associated speck-like protein containing a caspase activation and recruitment domain (ASC), and caspase-1, were significantly increased in a time-dependent manner in bone cancer pain." (PMID 35592413, 2022).
Bovine mastitis (3 papers, 2018 to 2023). INFLAMMATION of the UDDER in cows. "Hence, it can be concluded that the expression of lncRNA XIST during bovine mastitis is caused by the activation of NF-kB and lncRNA XIST negatively regulated the expression of NLRP3 inflammasome to prevent excessive inflammation in bovine mastitis." (PMID 33101288, 2020). "In summary, these results suggest that SPB ameliorates the inflammatory response induced by S. aureus LTA via suppressing the TLR2/NF-κB/NLRP3 signaling pathway, which indicates that SPB may be a potential agent for the treatment of bovine mastitis." (PMID 30469547, 2018). "Zophobas morio (Z. morio) hemolymph can decrease the levels of NLRP3, caspase-1 and NLRP6 and inhibit the secretion of IL-1β and IL-18, thereby attenuating E. coli- or Staphylococcus simulans (S. simulans)-induced pyroptosis; thus, it can be a new therapeutic candidate for bovine mastitis." (PMID 37845761, 2023).
C. perfringens infection (3 papers, 2018 to 2024). "The toxins lecithinase and perfringolysin O of C. perfringens have been found to activate the NLRP3 inflammasome, and NLRP3 deficiency leads to increased host susceptibility to C. perfringens infection." (PMID 38622656, 2024). "Further studies investigating the interplay between lecithinase and PFO or therapeutic blockade of NLRP3 would provide more treatment options for patients with C. perfringens infection." (PMID 37073791, 2023). "Real-time PCR confirmed that host TLR2 and NLRP3 inflammasome genes were induced in response to C. perfringens infection." (PMID 29588405, 2018).
cerebellar degeneration (3 papers, 2022 to 2025). Degeneration of the cerebellum. "To explore the mechanism underlying the protective effect of MCC950 in METH-induced cerebellar degeneration, we conducted an immunoblotting analysis of NLRP3 pathway proteins including NLRP3, ASC, Caspase-1, Cleaved Caspase-1 (P20), IL-1β and mature IL-1β." (PMID 35431795, 2022). "To explore the mechanisms involved in the METH-induced cerebellar degeneration, we quantified NLRP3-ASC-Caspase 1-IL-1β pathway protein levels." (PMID 35431795, 2022). "Mouse models showed that NLRP3 inhibition could prevent motor deficits and cerebellar degeneration induced by chronic Meth administration, implying the potential therapeutic roles of NLRP3 inflammasome on neurological symptoms in chronic Meth users." (PMID 37371502, 2023). "Given that inflammatory factors may trigger neuronal dysfunction, we hypothesize that NLRP3 inhibition can alleviate cerebellar degeneration via modulation of inflammation." (PMID 35431795, 2022). "Collectively, these findings suggest that mature IL-1β secretion mediated by NLRP3-ASC-Caspase 1 may be a critical step in METH-induced cerebellar degeneration and highlight the neuroprotective properties of inflammasome inhibition in cerebellar degeneration." (PMID 35431795, 2022).